ERBB4 (erb-b2 receptor tyrosine kinase 4)
Diseases named in the same sentence as ERBB4 in open-access papers (continued):
Sharing a sentence is not in itself a finding about the gene and the disease.
viral infection (2 papers, 2019 to 2023). "While ErbB1 has been implicated in the life cycle of multiple RNA and DNA viruses, its precise role in coronavirus infections, its role in alphavirus infections, and the roles of ErB2 and ErbB4 in any viral infection remained unknown." (PMID 37581931, 2023).
/T-cell lymphomas (1 paper, 2012). "The up-regulation of IL1A was previously shown in EBV-positive NK/T-cell lymphomas along with mRNAs of other genes thought to be involved in cell proliferation such as BCL6 or ERBB4." (PMID 22870299, 2012).
acute kidney injury (1 paper, 2023). Sudden and sustained deterioration of the kidney function characterized by decreased glomerular filtration rate, increased serum creatinine or oliguria. "We have previously reported that global deletion of ErbB4 resulted in increased tubulointerstitial fibrosis in response to acute kidney injury, suggesting a potential role to counteract the effects of EGFR42." (PMID 37963889, 2023).
adenoma (1 paper, 2019). A neoplasm arising from the epithelium. "EGFR, a subtype of the ErbB receptors, which include EGFR (ErbB1, HER1), p185her2/neu (ErbB2, HER2), ErbB3 (HER3), and ErbB4 (HER4), can regulate cell motility and adhesion, adenoma invasion, angiogenesis, and adenoma cell proliferation." (PMID 31798535, 2019).
Aortic dissection (1 paper, 2025). Aortic dissection refers to a tear in the intimal layer of the aorta causing a separation between the intima and the medial layers of the aorta. "This study investigates the role of Erb-B2 receptor tyrosine kinase 4 (ERBB4) in aortic dissection (AD) pathogenesis and its potential as a therapeutic target in cell-based therapies." (PMID 40227858, 2025).
CADASIL (1 paper, 2016). "Collectively, these findings support the concept that the diminished myogenic tone and CBF deficits in CADASIL are caused by TIMP3-mediated suppression of the ADAM17/HB-EGF/(ErbB1/ErbB4) pathway." (PMID 27476853, 2016).
cerebral malaria (1 paper, 2018). A sequestration of Plasmodium falciparum in the brain, which can cause coma and/or seizures. "Our interest in signal transducer and activation of transcription 3 (STAT3) and AKT signaling pathways derives from the reported importance of STAT3 in the pathogenesis of cerebral malaria while AKT activation is a typical downstream signal molecule for NRG-1/ErbB4." (PMID 29636063, 2018).
cholesteatoma (1 paper, 2013). A pathologic process characterized by the proliferation of keratinizing squamous epithelium resulting in the accumulation of keratin and cells in the middle ear and/or mastoid. "Immunohistochemistry of cholesteatoma tissues and retroauricular skin samples revealed strong expression of both EGFR and ErbB4 by the epithelial cells of both cholesteatoma and retroauricular skin." (PMID 23826119, 2013).
chordoma (1 paper, 2021). Chordomas are rare malignant tumors arising from embryonic remnants of the notochord in axial skeleton. "Furthermore, EGFR activation has also been reported, and an European multi-center trial is evaluating the efficacy of afatinib, an ERBB family (EGFR/ERBB1, HER2/ERBB2, ERBB3, and ERBB4) inhibitor, as first-line or later-line treatment in advanced chordoma (NCT03083678)." (PMID 34868903, 2021).
Chronic colitis (1 paper, 2021). A chronic inflammatory disease of the large intestine (colon, cecum and rectum). "This study extends these findings to identify the specific role of acute NRG4/ErbB4 signaling in macrophages and the impact that loss of ErbB4 in macrophages has on acute and chronic colitis." (PMID 33826403, 2021).
ciliopathy (1 paper, 2021). A genetic disorder of the cellular cilia or the cilia anchoring structures, the basal bodies, or of ciliary function. "This indicates that pathogenic CRD-NRG1 signals affecting the ventricular system derive from cells other than glutamatergic neurons, eg, ependymal cells, possibly causing abnormal autocrine NRG1/ErbB4 signaling, ciliopathy, and altered cerebrospinal fluid circulation." (PMID 33871014, 2021).
Crohn's colitis (1 paper, 2019). Crohn's disease affecting the colon. "ERBB4 is highly expressed in Crohn’s colitis and is upregulated by activation of nuclear factor kappa (NF-κB)." (PMID 31497384, 2019).
dementia (1 paper, 2024). Loss of intellectual abilities interfering with an individual's social and occupational functions. "The EGFR subunit ErbB4 and p-tauSer202 are overexpressed and colocalized in progressive supranuclear palsy (PSP), a form of dementia." (PMID 39434878, 2024).
diabetic cardiomyopathy (1 paper, 2022). Diabetic cardiomyopathy is a disorder of the heart muscle in people with diabetes. "The expression of cardiac NRG1 and the phosphorylation of ErbB2 and ErbB4 are reduced in in vitro (cellular) and in vivo (rat models) of diabetic cardiomyopathy." (PMID 35370955, 2022).
embryonal carcinoma (1 paper, 2020). A non-seminomatous malignant germ cell tumor characterized by the presence of large germ cells with abundant cytoplasm resembling epithelial cells, geographic necrosis, high mitotic activity, and pseudoglandular and pseudopapillary structures formation. "Based on our results, we suggest that KIT, TNFRSF8, and ERBB4 may be suitable targets for the treatment of germinoma, embryonal carcinomas, and yolk sac tumors, respectively." (PMID 32999426, 2020).
gallbladder cancer (1 paper, 2021).
gastric tumour (1 paper, 2021). "Using mass spectrometry-based genotyping we analysed 105 hotspot, non-synonymous somatic mutations in PIK3CA and ERBB-family (EGFR, ERBB2, ERBB3 and ERBB4) genes in gastric tumour samples from 69 patients." (PMID 33933113, 2021).
genetic generalized epilepsy (1 paper, 2024). A generalized epilepsy that is understood to have a genetic etiology. "ErbB4 variants or exonic deletions are associated with genetic generalized epilepsy and early myoclonic encephalopathy." (PMID 38388921, 2024).
germinoma (1 paper, 2020). A malignant germ cell tumor arising in the central nervous system. "Based on our results, we suggest that KIT, TNFRSF8, and ERBB4 may be suitable targets for the treatment of germinoma, ECs, and YSTs, respectively." (PMID 32999426, 2020).
Glucose intolerance (1 paper, 2023). Glucose intolerance (GI) can be defined as dysglycemia that comprises both prediabetes and diabetes. "Oxt neuron‐specific knockdown of ErbB4 resulted in glucose intolerance." (PMID 37060105, 2023).
Hirschsprung disease (1 paper, 2021). Hirschsprung disease (HSCR) is a congenital intestinal motility disorder that is characterized by signs of intestinal obstruction due to the presence of an aganglionic segment of variable extent in the terminal part of the colon. "By acting on ErbB4, NRG3 promotes the development of Hirschsprung disease (HSCR)." (PMID 34484469, 2021).
hypertensive heart disease (1 paper, 2023). Abnormal enlargement of the heart resulting from long-standing hypertension. "Next, we determined the pathogenic role and therapeutic effect of Erbb4-IR on Ang II-induced hypertensive heart disease by ultrasound-microbubble-mediated overexpression of Erbb4-IR shRNA." (PMID 37449045, 2023). "However, it is unclear whether Erbb4-IR plays a pathogenic role and whether it could be a therapeutic target for hypertensive heart disease." (PMID 37449045, 2023). "However, the role of Erbb4-IR in hypertensive heart disease remains unexplored and was investigated in the present study by ultrasound-microbubble-mediated silencing of cardiac Erbb4-IR in hypertensive mice induced by angiotensin II." (PMID 37449045, 2023). "In conclusion, Erbb4-IR is pathogenic in angiotensin II (Ang II)-induced cardiac remodeling, and targeting Erbb4-IR may be a novel therapy for hypertensive cardiovascular diseases." (PMID 37449045, 2023). "Thus, targeting Erbb4-IR may be a novel and effective therapy for hypertensive cardiovascular disease." (PMID 37449045, 2023).
hypoplastic left heart syndrome (1 paper, 2025). Hypoplastic left heart syndrome (HLHS) refers to the abnormal development of the left-sided cardiac structures, resulting in obstruction to blood flow from the left ventricular outflow tract. "Specifically, NRG1 and its receptor ERBB4 have been shown to be associated with LVOT defects, including AS, coarctation of the aorta, and hypoplastic left heart syndrome." (PMID 40149647, 2025).
Immunodeficiency (1 paper, 2020). Failure of the immune system to protect the body adequately from infection, due to the absence or insufficiency of some component process or substance. "Besides, this study also indicated that LF must be used very cautiously to treat women during pregnancy or patients with immunodeficiency, because LF triterpenoids might cause embryo toxicity and immune suppression by inhibiting the activity of ErbB4 and Lck." (PMID 33246450, 2020).
Impaired glucose tolerance (1 paper, 2023). An abnormal resistance to glucose, i.e., a reduction in the ability to maintain glucose levels in the blood stream within normal limits following oral or intravenous administration of glucose. "ERBB4 encodes a receptor tyrosine kinase expressed in liver and pancreas, and ERBB4 disruption has been linked to impaired glucose tolerance and reduced insulin response in mice, supporting its possible effect on obesity." (PMID 37794188, 2023).
infertile (1 paper, 2025). "Another study performed exome sequencing on either gamete donors or infertile patients undergoing in vitro fertilization treatment without any known family history of inheritable genetic conditions, identifying an asymptomatic individual carrying the ERBB4 c.1630C > T (p.R544W) variant." (PMID 40469844, 2025).
inflammatory bowel disease (1 paper, 2023). A spectrum of small and large bowel inflammatory diseases of unknown etiology. "In inflammatory bowel disease, ErbB4 is involved in the regulation of inflammatory M1/M2 transformation through the interaction with STAT1 and STAT5." (PMID 37800117, 2023). "Activation of ErbB4 can induce macrophage apoptosis in a mouse model of inflammatory bowel disease, thereby inhibiting intestinal inflammation." (PMID 37800117, 2023).
liver disease (1 paper, 2016). "The role of ERBB4 in liver disease has seldom been reported." (PMID 26701850, 2016).
low grade glioma (1 paper, 2021). A grade I or grade II glioma arising from the central nervous system. "Furthermore, we identified that Caucasian CCLs in low-grade glioma (LGG) were more sensitive to irreversible tyrosine kinase inhibitors (TKI) targeting EGFR, ERBB2 or ERBB4, such as AST-1306 (Cohen’s d = 1.71, adj." (PMID 34576298, 2021).
lung disease (1 paper, 2018). "From these data, we speculate that genetic variants that suppress neuregulin/EGFR/ErbB4 signaling may also contribute to severity of lung disease in a subset of infants with adverse respiratory outcomes." (PMID 30342483, 2018).
malignant bone tumors (1 paper, 2021). "The ERBB4 signaling, in addition to PIK3/AKT, has been suggested as a potential target for treatment of malignant bone tumors." (PMID 33801830, 2021).
metastatic colorectal cancer (1 paper, 2016). "As a member of the EGFR family, ERBB4 is frequently activated in brain metastases and metastatic colorectal cancer." (PMID 27270314, 2016).
motor neuron degeneration (1 paper, 2019). "Mutations in the ALS19 gene lead to the reduced autophosphorylation capacity of the ErbB4 protein upon stimulation with NRG‐1, suggesting that the disruption of the NRG–ErbB4 pathway causes motor neuron degeneration." (PMID 31124187, 2019).
Myocardial fibrosis (1 paper, 2023). "H&E and Masson’s trichrome staining revealed moderate myocardial fibrosis, identified by extracellular matrix deposition in Ang II-induced hypertensive mice, which was abrogated in those treated with Erbb4-IR shRNA but not by the EV control." (PMID 37449045, 2023).
myocarditis (1 paper, 2019). Myocarditis is a condition that is characterized by inflammation of the heart muscle (myocardium). "Therefore, NRG-1 and its receptor ERBB4 may be of central importance to the recovery from acute and chronic CVB3 induced myocarditis." (PMID 31396490, 2019).
oncocytoma (1 paper, 2019). "ErbB4, Insulin R, and IGF-1R were phosphorylated in the papillary RCC (RE0020), Mer (Axl family) was phosphorylated in the oncocytoma (RE0150), and HGFR, PDGFRα, and PDGFRβ were phosphorylated in the renal pelvic carcinoma (RE0210)." (PMID 31690270, 2019).
oral cavity cancer (1 paper, 2020). A primary or metastatic malignant neoplasm involving the oral cavity.
paroxysmal AF (1 paper, 2018). "Our investigation demonstrated a potential mechanism of the NRG1/ErbB4 signaling system in a paroxysmal AF model." (PMID 30246788, 2018). "Therefore, pharmacological regulation of the NRG1/ErbB4 pathway is a potential treatment for patients in an early stage of AF (e.g., paroxysmal AF)." (PMID 30246788, 2018). "The detailed mechanism by which ErbB4 and nitric oxide synthase function in paroxysmal AF is not known." (PMID 30246788, 2018).
peripartum cardiomyopathy (1 paper, 2022). Peripartum cardiomyopathy (PPCM) is an idiopathic, potentially fatal form of dilated cardiomyopathy that develops during the final month of pregnancy or within five months after delivery. "The downregulation of the ERBB4 Tyrosine kinase receptor by miR-130 leading to increased left ventricle dilation and hypertrophy was found in the condition of peripartum cardiomyopathy." (PMID 36071532, 2022).
peripheral nerve injuries (1 paper, 2023). "Moreover, the decreased expression of Erbb4 inhibited nerve regeneration and participated in peripheral nerve injuries postoperatively." (PMID 37765280, 2023).
prediabetes (1 paper, 2025). "Our findings not only expand the understanding of the association between prediabetes and VD, but also reveal a relationship between ErbB4 and cardiac ferroptosis in prediabetic conditions." (PMID 40746531, 2025).
pterygium (1 paper, 2020). A wedge-shaped fibrovascular lesion arising from the bulbar conjunctiva and extending to the cornea. "We presume that the LINC00472 network might function in pterygium via the FOXM1 PATHWAY, especially through the regulation of CCNB1, MYC, ERBB4, RELN, RB1, and CDH2 in the ceRNA network." (PMID 33299863, 2020). "There are 6 genes that are highly expressed in pterygium, MYC, CDH2, CCNB1, RELN, RB1, and ERBB4." (PMID 33299863, 2020).
Renal cyst (1 paper, 2017). A fluid filled sac in the kidney. "Overexpression of ErbB4 in mice induced renal cysts, whereas deletion attenuated disease progression in the Cpk mouse model." (PMID 28558802, 2017).
respiratory distress syndrome (1 paper, 2023). "Downregulation of the ERBB4 gene is responsible for insufficient fetal surfactant production which further leads to respiratory distress syndrome in preterm infants." (PMID 37260775, 2023).
spindle cell neoplasm (1 paper, 2019). A benign or malignant neoplasm characterized by the presence of neoplastic spindle cells. "It will also be of great interest to establish the relative contributions that canonical membrane-based erbB4 signaling and transcriptional signaling by the erbB4 intracellular domain make to the development of these aggressive spindle cell neoplasms." (PMID 31291965, 2019).
status epilepticus (1 paper, 2017). Status epilepticus is defined as a continuous seizure lasting more than 30 min, or two or more seizures without full recovery of consciousness between any of them. "Here, we examined the contribution of neuropsin–NRG1 signaling to the pathological functions of ErbB4-expressing, parvalbumin-positive GABAergic interneurons in the kainate (KA)-induced status epilepticus mouse model." (PMID 28267150, 2017).
steatosis (1 paper, 2025). Increased lipid within the cytoplasm of cells. "Specialized themes also encompass the pink cluster as a niche theme regarding exercise-induced myokines such as neuregulin-4 (Nrg4), which mitigates steatosis via Nrg4/ErbB4/AKT signaling and demonstrates rapid effects on hepatic lipid metabolic reprogramming following sleeve gastrectomy." (PMID 40868109, 2025).
Tourette syndrome (1 paper, 2026). A neurologic disorder caused by defective metabolism of the neurotransmitters in the brain. "Both genes contribute to a protein interaction network including ERBB4 and RAPGEF1 which we had previously identified in a large Tourette Syndrome pedigree." (PMID 42078338, 2026).
Tremor (1 paper, 2018). An unintentional, oscillating to-and-fro muscle movement about a joint axis. "Once again, we found that anti-NRG1, but not anti-ErbB3/anti-ErbB4 combination treatment caused tremor and a decrease in rearings." (PMID 29844389, 2018). "Moreover, treatment with a combination of both anti-ErbB3 and anti-ErbB4 inhibitory antibodies did not result in tremor or sensorimotor gating deficits, further supporting a receptor-independent mechanism of the anti-NRG1 phenotypes." (PMID 29844389, 2018). "However, we saw no tremor, or observable motor changes in anti-ErbB4 treated mice, indicating that the observed effects of anti-NRG1 likely did not depend on receptor mediated signaling." (PMID 29844389, 2018).
type 1 diabetes nephropathy (1 paper, 2021). Diabetic nephropathy is a progressive kidney disease caused by angiopathy of capillaries in the kidney glomeruli. "Further, ERBB4 genetic variants are associated with T2DM and type 1 diabetes nephropathy." (PMID 33801830, 2021).
viral myocarditis (1 paper, 2019). Myocarditis that is caused by an infection with a viral agent. "Employing a well-established murine model of viral myocarditis, we showed that Nup98, Nrg1, and erbB4 are all upregulated in the myocardium during the acute phase (7 dpi)." (PMID 31396490, 2019).